EGFR (epidermal growth factor receptor)
Diseases named in the same sentence as EGFR in open-access papers (continued):
Sharing a sentence is not in itself a finding about the gene and the disease.
tumor (continued). "Clinically, EGFR inhibitors such as Erlotinib were used to repress EGFR signaling activations and suppress tumor cell growth." (PMID 27356755, 2016). "In this trial, patients had recurrent disease and the only histological requirement was EGFR expression in the tumor." (PMID 27888810, 2016). "In summary, this is the first report supporting a mechanism of EHD3-mediated tumor suppression that involves the attenuation of endosomal signaling of the EGFR oncogene." (PMID 27811356, 2016). "In accordance with the findings from the mRNA sequencing data, TIM-3, LAG-3 and CTLA-4 were expressed at higher levels in both CD4 and CD8 T cells from PD-1 resistant as compared with untreated EGFR TL tumours by flow cytometry analysis." (PMID 26883990, 2016). "In vitro studies further demonstrate that necitumumab inhibits EGFR-dependent tumour cell proliferation, and can exert cytotoxic effects in tumour cells through antibody-dependent cell-mediated cytotoxicity." (PMID 26766738, 2016). "Generally, we observed a trend of epithelial markers (EpCAM, CK18, CK19, EGFR) to be downregulated in CTCs compared to the bulk tumor cells derived from hepatic metastases, of these genes EGFR reached statistical significance (p = 0.019)." (PMID 27029058, 2016). "MEK and PI3K inhibitors can inhibit cell proliferation in NSCLC; however, for apoptosis activation, both signaling pathways must be simultaneously inhibited, a situation that is directly related to the frequently observed EGFR-TKI resistance in this tumor." (PMID 27098372, 2016). "Suppressing Spry1 reverses these phenotypes by impairment of EGFR signaling, and leads to a significant reduction in tumor growth in vivo." (PMID 26976794, 2016). "In colorectal cancer patients, LSC6 polymorphism in the let-7 binding site of the KRAS gene, has been proposed to predict the tumor responsiveness in EGFR-directed (cetuximab) treated patients." (PMID 26646588, 2016). "Classically, EGFR is widely acknowledged for its influence in tumour biology and wound healing and at least six EGFR‐specific inhibitors have been used in clinical cancer therapy." (PMID 26762600, 2016). "In vivo, we injected EGFR siRNA‐MB or miR‐133a‐MB into mice and examined the tumor size and survival rate." (PMID 27465833, 2016). "More than a half of the compounds showed acceptable EGFR inhibition activities over wild-type tumor cells but obviously weak activities over T790M mutant tumor cells." (PMID 27983649, 2016). "Excess ADAM17 activity leads to an increased release of EGFR ligands, which can drive tumour progression, whilst low ADAM17 activity can cause problems in development and regeneration due to decreased EGFR signalling." (PMID 27731361, 2016). "Use of circulating tumour DNA (ctDNA) has identified emergence of RAS mutations following cetuximab administration, conferring resistance to EGFR-targeted therapy." (PMID 27340376, 2016). "The epidermal growth factor receptor (EGFR), a transmembrane receptor tyrosine kinase, is overexpressed in a variety of cancers, and associated with tumor progression and poor prognosis." (PMID 27659529, 2016). "First, we analysed EGFR and HER2 alterations by using immunohistochemistry (IHC) to select the tumours with moderate/strong expression of EGFR or HER2 protein." (PMID 27387915, 2016). "EGFR is abnormally activated in many epithelial cells and its signaling can provide substantial advantage in tumor cells survival." (PMID 27732953, 2016). "Our data emphasize the importance of signaling pathway activity, in addition to the genetic status of EGFR, in tumor cell behavior and aggressiveness." (PMID 27738329, 2016). "Immunoprecipitation of tumor tissue lysates showed that the in vivo down-regulation of CAGE prevented the interaction of CAGE with EGFR and HER2 and the interaction between EGFR and HER2." (PMID 26863629, 2016).
tumor (continued). "Recently, second-generation EGFR TKIs that inhibit EGFR activity by irreversibly binding to EGFR have been clinically developed and have shown promising anti-tumor activity in NSCLC." (PMID 27283902, 2016). "Epidermal growth factor receptor (EGFR) activation has been shown to play a critical role in tumor angiogenesis." (PMID 27362942, 2016). "The use of EGFR specific antibodies for cancer therapy is promising, but serious problems can be envisioned, due to heterogeneity within the tumor and the fact that normal cell also expresses EGFR." (PMID 26778701, 2016). "Our in vitro and in vivo studies support a tumor suppressive role of miR-3622b in PCa, mediating its effects largely by directly repressing Epidermal Growth Factor Receptor (EGFR)." (PMID 27611943, 2016). "Subsequently, the total RNA and protein were extracted from each tumor and used to evaluate the expression levels of miR-218-5p and EGFR." (PMID 27057632, 2016). "In summary, our study provides the first evidence suggesting the possible role of IL-17E in tumor resistance to anti-EGFR therapeutic agents." (PMID 27462789, 2016). "The Akt pathway also regulates cell proliferation and survival, and increased tumor growth was observed in tumors with mutant EGFR in our and other studies." (PMID 27362942, 2016). "On the other hand, ginsenoside Rg3 induces tumor cell apoptosis through decreasing cell surface EGFR." (PMID 27655708, 2016). "We have also reported that loss of EGFR protein upon knock-down of the E3 ligase SMURF2, induced autophagy and sensitized tumor cells." (PMID 27612423, 2016). "Here we have investigated possible mechanisms of tumor resistance to EGFR inhibition in both EGFR mutant and wild type NSCLC cells in order to optimize the use of small molecule therapies directed against the EGFR in a broad range of patients." (PMID 27248176, 2016). "Two K + V- diploid replicates have a variant frequency profile consistent with the stromal sample, and lack the somatic EGFR deletion detected in K + V- tumor DNA aneuploid cells." (PMID 26864208, 2016). "Immunohistochemistry results revealed both cytoplasmic and nuclear EGFR expression with variable degrees between tumours." (PMID 26870997, 2016). "In malignancy, tumor microenvironment produces certain EGFR ligands which constantly stimulate EGFR." (PMID 27051190, 2016). "Almost all received prior oxaliplatin and irinotecan (99 %), 92 % had prior bevacizumab, and 283/291 (97 %) of patients with KRAS wild-type tumours had previously received anti-EGFR therapy." (PMID 27389564, 2016). "dsRBEC is an efficient vector for targeting polyIC into EGFR over-expressing tumor cells, leading to apoptosis and cytokine secretion." (PMID 27598772, 2016). "Tumour EGFR protein expression status was evaluable for 37 of the 44 enrolled patients; data were missing for five patients, and the analysis was not performed for two patients." (PMID 26766738, 2016). "TUSC2/erlotinib is currently in Phase II clinical trials in stage 4 NSCLC patients who are EGFR wildtype and have tumor progression on other treatments." (PMID 27845352, 2016). "Here we find that patients who experience greater and longer responses to EGFR blockade preferentially develop EGFR ECD mutations, while RAS mutations emerge more frequently in patients with smaller tumour shrinkage and shorter progression-free survival." (PMID 27929064, 2016). "Together, these data indicate that the presence of IL-17E within the TNBC tumor microenvironment probably promotes and sustains EGFR activation and translocation and ultimately results in tumor resistance." (PMID 27462789, 2016). "Here we present specific and high contrast in vivo visualization of small human tumours overexpressing EGFR by preclinical multi-pinhole SPECT shortly after administration of anti-EGFR nanobody 99mTc-D10." (PMID 26912069, 2016).
tumor (continued). "To assess the in vivo effects of the drug combination on apoptotic and EGFR signaling pathway proteins, we preformed Western blotting of lysates from excised tumor xenografts after treatment." (PMID 27283902, 2016). "Previous studies in NSCLC patients also showed an early (2–14 days) reduction of 18F-FDG uptake in response to treatment with EGFR TKIs that was predictive of morphovolumetric tumor response, PFS, and OS." (PMID 27726115, 2016). "Instead, secondary events, such as inflammation-induced signaling activation of the epidermal growth factor (EGFR) or induction of Sox9 expression, are required for tumor formation." (PMID 26697077, 2016). "Further, the biologic relationship between Mg and cancer progression is unclear, and there is no definite evidence to suggest that Mg supplementation reverses the anti-tumor effects of EGFR inhibition." (PMID 27683640, 2016). "Although the FDA approved EGFR monoclonal antibody cetuximab demonstrates some clinical activity, this approach has shown limited success due to unexplained poor tumor responses and the rapid development of drug resistance." (PMID 27738319, 2016). "Formalin fixed tumour specimens collected from 184 naive NSCLC patients were analysed independently by the ARMS-PCR and SMART assays for the presence of EGFR mutations." (PMID 27409166, 2016). "In this study, we aimed to discover novel mechanisms of primary resistance to EGFR TKIs by using patient tumor samples from a large-scaled, prospective trial." (PMID 27121209, 2016). "Several studies have reported that JAG1 mediates multiple signaling pathways such as: AP-1, MAPK, EGFR, NF-κβ, and IL-6 in different tumor cells." (PMID 26930648, 2016). "Although the majority of both EGFR and KRAS mutant cases were M1b, only 2/22 (9%) EGFR mutant cases had the primary tumor resected versus 4/8 (50%) KRAS mutant patients." (PMID 27448974, 2016). "It is designed to release an irreversible EGFR TKI within hypoxic regions of tumours, thereby improving selectivity and circumventing some of the toxicities observed with existing EGFR TKIs." (PMID 26811177, 2016). "Expression of ERBB3 has, similar to EGFR in our CTC predictor, previously been associated with endocrine therapy resistance when highly expressed in primary tumor tissue." (PMID 26892682, 2016). "Analysis of 17 metachronous paired tumors showed frequent biomarker changes, including MGMT-methylation and EGFR aberrations, indicating the need for a re-biopsy for tumor profiling to direct subsequent therapy." (PMID 26933808, 2016). "The direct inhibition of EGFR translation by miR-218-5p and the potential role of miR-218-5p as a tumor suppressor in NSCLC development have been experimentally validated in vitro and in vivo." (PMID 27057632, 2016). "The efficacy of in vivo tumour detection with anti-EGFR nanobody 99mTc-D10 was compared to the IgG199mTc-Cetuximab that was used to visualize A431 tumour lesions with comparable mean tumour volumes of 40 mm3 (N = 5; range 7–90 mm3) 45 min post injection." (PMID 26912069, 2016). "Therapeutic targets such as the HER2, EGFR, or PD-L1 have been analyzed, combined with genetic analysis in other tumor entities and with genomic analysis of resistance genes." (PMID 27145459, 2016). "Although we have demonstrated the tumour suppressive role of miR‐134 in NSCLC via targeting EGFR, our study does have specific limitations." (PMID 27241841, 2016). "Collectively, these findings have significant clinical implications for patients with tumours harbouring high EGFR expression due to the possible high sensitivity of this regimen." (PMID 27105508, 2016). "Upon subsequent re-challenge with anti-EGFR antibodies, the tumor again responded to EGFR blockade, despite prior resistance." (PMID 27608848, 2016). "EGFR also plays a significant role in tumor development and progression, including cell proliferation, regulation of apoptotic cell death, angiogenesis and metastatic spread." (PMID 26918608, 2016).
tumor (continued). "Exposure of tumor cells to radiation results in immediate activation of EGFR by autophosphorylation and a secondary prolonged release of TGF-α." (PMID 26909338, 2016). "The similar case is SH3GL2, deletion of which downregulates tumor growth by modulating EGFR signaling." (PMID 27610367, 2016). "In a separate study we investigated the effect of the EGFR specific mAb cetuximab (CET) on the A431 xenograft tumor growth as well as the combination therapy of cetuximab and genistein (GEN-CET)." (PMID 27070087, 2016). "EGFR875-889-specific CD4 T cells can be detected in the peripheral blood of HNSCC patients, and was shown to react against tumor cells expressing EGFR as well as other ErbB/HER family members (HER-2, HER-3) and c-kit, which have homologous peptide sequences." (PMID 27833557, 2016). "Previous studies found that there is a significant enrichment of H3K4Me3 modification in the TSS regions of MYC and EGFR genes in many tumor cells." (PMID 27087825, 2016). "Compared with the EGFR mutation and EML4-ALK rearrangement patients, KRAS mutation patients demonstrated unique features in terms of tumor site, pathology stage and smoking status." (PMID 26739511, 2016). "Our laboratory in preclinical models has demonstrated synergistic cytotoxicity with high-dose statins and EGFR-TKIs across a number of tumour types." (PMID 27036206, 2016). "Therefore, anti-EGFR nanobody 99mTc-D10 might be suitable in a clinical setting as non-invasive diagnostic tracer to not only detect small tumours but also to obtain information on the expression level of EGFR at the time of diagnosis and during disease progression." (PMID 26912069, 2016). "Following in vivo passage and selection of tumor progenitor cells, the relative differences in EGFR activity were preserved." (PMID 27738329, 2016). "Third, the data in this study were quite heterogeneous with relatively small number of patients with different tumor types and different targeted agents used (EGFR–TKI or VEGF–TKI)." (PMID 26885610, 2016). "When EGFR is activated or E-cadherin is inactivated, the most obvious changes occur on the tumor cell membrane, while cytoplasmic vimentin is one of the best indicators of EMT in HNSCC." (PMID 27172790, 2016). "DARPins can be expressed in the cytoplasm of E. coli, and recently the inhibitory effects on tumor cell growth of DARPins targeting EGFR were reported together with a detailed inhibitory mechanism." (PMID 27419062, 2016). "Combination treatment was more effective in reducing tumor size and EGFR activation than either agent alone." (PMID 27283902, 2016). "The dimer binds to EGFR and cytochromes P450 to enhance tumour cell proliferation and chemoresistance." (PMID 26988023, 2016). "We and others have noted that EGFR degradation upon gemcitabine, cisplatin or radiation increases tumor cell-specific cytotoxicity beyond that of EGFR inhibition alone, and TKI-resistant cells are responsive to therapies that induce EGFR degradation." (PMID 27612423, 2016). "MiR-128b loss of heterozygosity in chromosome 3p is frequent in NSCLC tumor samples and was significantly correlated with clinical response to targeted EGFR inhibition following gefitinib treatment." (PMID 26646588, 2016). "In fact, since the introduction of the first inhibitors, it has become clear that clinical responses obtained in EGFR-mutant sensitive tumours were limited in time and that resistance would inevitably occur." (PMID 27350784, 2016). "Although EGFR is identified as an important anti-tumor target, therapies against EGFR using small tyrosine kinase inhibitors such as Gefitinib, Lapatinib and Erlotinib have been shown to have limited effectiveness in PCa." (PMID 27152724, 2016).
tumor (continued). "Some molecules that play important roles in tumor development signaling pathways such as epidermal growth factor receptor (EGFR), human epidermal growth factor receptor-2 (HER2) are Hsp90AB1 client proteins." (PMID 26903158, 2016). "EGFR is known to regulate tumor progression and the autophagic process, but the role of TKI sensitivities/resistant mutation in autophagic death is not clear." (PMID 27612423, 2016). "Cetuximab (IgG1 chimeric) and panitumumab (IgG2 fully humanized) are clinically approved anti-EGFR mAbs that bind to the extracellular domain of EGFR thereby blocking EGFR dimerization, resulting in apoptosis and preventing tumor growth." (PMID 27314237, 2016). "Here, we show that the anti-EGFR nanobody 99mTc-D10 is suitable to visualize small tumour lesions with weights below 100 mg corresponding to tumour volumes below 100 mm3." (PMID 26912069, 2016). "Over-activation of EGFR and its downstream signalling pathways is prominent in drug-resistant tumour tissues." (PMID 27249340, 2016). "From a cohort of 192 TNBC patients, this study identified five significant clinical variables/biomarkers, including pathological tumor stage, nodal stage, EGFR, CK5/6 and Ki-67." (PMID 26930401, 2016). "The main mechanisms of gefitinib are the activation of AMPK signaling pathway interfered with tumor cells metabolism and inhibition on the EGFR signaling pathway significantly." (PMID 27334428, 2016). "Unfortunately, preclinical EGFR antibody-based imaging studies revealed a mismatch between in vivo EGFR protein expression and tumor tracer uptake." (PMID 27602494, 2016). "In contrast, other alterations like overexpression of the epidermal growth factor receptor (EGFR) are present in tumor-adjacent, morphologically normal mucosa." (PMID 27716615, 2016). "We then tested the relation between COX-2 mRNA expression levels and both EGFR mRNA level and PIK3CA mutation status, previously determined in these tumor samples." (PMID 27835884, 2016). "Higher 89Zr-imgatuzumab tumor uptake was found in H441 compared to A549 xenografts in our study, despite lower in vitro and ex vivo EGFR expression based upon ELISA." (PMID 27602494, 2016). "These include the use of monoclonal antibodies against the epidermal growth factor receptor (EGFR) in patients with KRAS wild‐type (WT) tumours, although only a minority of patients respond to this approach." (PMID 26690310, 2016). "Based on these results, the EGFR-pathway appears to be more important for the formation of the tumor microenvironment than the Kras pathway, and IL10 appears to be crucial for the EGFRL858R-mediated tumor microenvironment." (PMID 26956044, 2016). "Dysregulation of the EGFR signaling cascade can result in rapid cell division ultimately supporting tumor growth." (PMID 27314237, 2016). "We previously reported that long-term inhibition of PI3K leads to EGFR/PI3K-independent but MEK/ERK-dependent reactivation of Akt in tumor cells presenting constitutive K-Ras activity either through K-RAS mutation or overexpression of K-RASwt." (PMID 27248324, 2016). "In contrast, wild-type EGFR has been thought inappropriate for a target molecule of CAR-engineered T cells due to possible deleterious recognition of normal cells, because EGFR is expressed not only tumor cells but also normal cells at physiological levels." (PMID 27833557, 2016). "This is the first paper showing tumor uptake of an EGFR-targeted antibody tracer can be affected by EGFR shedding." (PMID 27602494, 2016). "Ligand-induced EGFR activation in particular plays a pivotal role in tumor proliferation, invasion, migration, and neovascularization through the RAS-RAF-MAPK and PI3K-AKT-mTOR pathways." (PMID 26989027, 2016). "In previous preclinical EGFR antibody-based imaging studies revealing mismatch between xenograft EGFR expression and tracer uptake, a large role was postulated for vascularity and vascular permeability for tracer delivery in the tumor." (PMID 27602494, 2016).